LEP (leptin)
Diseases named in the same sentence as LEP in open-access papers (continued):
Sharing a sentence is not in itself a finding about the gene and the disease.
breast cancer (continued). "Here, we incubated breast cancer cells with exogenous Leptin and noted that low concentrations of Leptin (0.625 nM) significantly stimulated the cell growth, enhanced cell viability, minimized apoptosis, and increased breast cancer cells entering the S phase." (PMID 27926517, 2017). "This may arise from cancer associated fibroblasts (CAFs) which have been recently shown to secrete leptin, mediating cross-talk between CAFs and breast cancer cells to drive growth and invasion, mammosphere formation and stemness." (PMID 28542577, 2017). "However, the molecular mechanisms whereby ER signaling mediates leptin-induced growth of breast cancer are not clearly understood." (PMID 29312618, 2017). "Some studies suggest that leptin may promote angiogenesis in breast cancer through the signaling of VEGF." (PMID 29311755, 2017). "Recent results show that activated farnesoid X receptor (FXR) may be able to counteract the leptin-dependent paracrine effects on breast cancer restraining the tumor-promoting activities exerted by CAFs." (PMID 29188139, 2017). "Leptin has been shown to induce the growth of breast cancer cells via autophagy induction." (PMID 29312618, 2017). "Numerous studies have previously shown that leptin can directly act on breast cancer cells and modulate their behavior, including promoting proliferation, transformation and reducing apoptosis, however the effect of leptin on the metastatic process is relatively poorly understood." (PMID 28542577, 2017). "Leptin has been found to be involved in breast cancer progression." (PMID 28930270, 2017). "Moreover, leptin-induced growth of MCF-7 breast cancer cells was significantly suppressed by pretreatment with tamoxifen, a selective ER modulator." (PMID 29312618, 2017). "Furthermore, serum ADIPO is reduced while LEP is increased breast cancer patients compared to healthy women." (PMID 28873415, 2017). "Thus, the results from the current study together with the previous reports demonstrate that ER signaling plays a crucial role in leptin-induced growth of breast cancer cells most probably through autophagy activation." (PMID 29312618, 2017). "Therefore, our results clearly demonstrate the role of ER signaling in the activation of AMPK/FoxO3A axis by leptin in breast cancer cells." (PMID 29312618, 2017). "Unquestionably definite proof is needed to elucidate leptin’s exact function in the growth and progress of breast tumors, as perception of leptin correlation with breast cancer can improve our awareness of breast carcinogenesis and support improving management and preventive plans." (PMID 29121911, 2017). "However, it is clear that the ADIPO:LEP ratio still displays a strong representation for accurately predicting the growth microenvironment that a breast cancer in an obese patient is exposed to in both post‐ and premenopausal women." (PMID 28676553, 2017). "For the identification of the procarcinogenic mechanisms of leptin, the breast cancer cell lines MCF-7, MDA-MB-231, and T47D have been characterized for the protein and its receptor [Ob-R), studying its effect over cell growth in the MCF-7, SK-BR-3, T47D, and ZR-75-1 cell lines." (PMID 29311755, 2017). "Leptin stimulates proliferation of breast cancer, hepatoma cells and prostate cancer." (PMID 28750624, 2017). "In addition, ER signaling utilizes the AMPK/FoxO3A axis to induce autophagy in leptin-treated breast cancer cells." (PMID 29312618, 2017). "Interestingly, the blockade of the IL-1 system, in breast cancer, inhibited leptin's effects on Notch expression, suggesting that leptin-induced Notch activation is reliant on IL-1 signaling." (PMID 28659656, 2017). "Moreover, blockade of autophagy induction also inhibited leptin-induced cyclin D1 expression, indicating that cyclin D1 would be a target molecule for autophagy- and ER signaling-mediated suppression of cell cycle progression by leptin in breast cancer cells." (PMID 29312618, 2017).
breast cancer (continued). "The relationship between TGFB1 and leptin signalling leads to the suggestion that treatment of obese breast cancer patients with drugs that can reduce leptin levels or antagonize TGFB1 signalling may be beneficial in prevention of metastatic disease." (PMID 28542577, 2017). "Leptin is one such molecule considered to mediate breast cancer progression." (PMID 28930270, 2017). "Thus, with both expression and intervention studies in two breast cancer cell lines, we extend the significance of the TGFB1 pathway to being a downstream mediator of leptin signalling for EMT / CSC changes in breast cancer cells." (PMID 28542577, 2017). "Interestingly, one study has reported higher leptin levels in breast cancer tissue compared to normal breast tissue from the same patient, suggesting elevated local production of leptin in the tumor microenvironment." (PMID 28542577, 2017). "In the present study, we analyzed by a multiplex ELISA plasma-blood assay, the expression of leptin, adiponectin and ghrelin in breast cancer patients and their healthy relatives belonging to families with Hereditary Breast Cancer Syndrome and with known BRCA1/2 gene molecular status." (PMID 29254161, 2017). "Thus, the present study was designed to identify the protective effects of six dietary compounds (quercetin, curcumin, gallic acid, EGCG, ascorbic acid and catechin) against the oncogenic actions of leptin in MCF-7 breast cancer cells in vitro." (PMID 28930270, 2017). "This suggests that higher circulating levels of leptin present in obese breast cancer patients might be contributing to the development of higher grade and more metastatic tumors by these direct actions of leptin on breast cancer epithelial cells." (PMID 28542577, 2017). "Our findings demonstrated that BMP9 could significantly inhibit the proliferation and migration of breast cancer cells and decrease the expression of leptin in pre-adipocytes and adipocytes of the co-culture system in vitro and in vivo." (PMID 28415788, 2017). "Also, breast cancer patients had lower concentrations of adiponectin and higher concentrations of leptin, IL-6, IL-8, TNF-α, resistin and visfatin than controls." (PMID 29088874, 2017). "This question is now under study in our Institute in a successive large series of subjects with same familial characteristics and aimed to confirm the effects of Adjuvant Endocrine treatment on serum Leptin, Serum Adiponectin and body composition of patients with breast cancer." (PMID 29254161, 2017). "Finally, we measured p21WAF1/CIP1 transcription activity changes in breast cancer cells with Leptin and SAHA treatment." (PMID 27926517, 2017). "A range of signaling mechanisms, including IL-6, IGF-1, leptin, and adiponectin, have been proposed to explain how mature adipocytes alter breast cancer cell behavior, but the role of adipocyte-derived fatty acids as direct metabolic substrates has not been investigated." (PMID 28101337, 2017). "In order to confirm the results, cells were co-incubated with IL-18 siRNA or IL-18BP-Fc chimeras and the effect of TAMs to promote migration and proliferation of breast cancer cells when stimulated by leptin was abrogated, thus proving the link between the process." (PMID 28970834, 2017). "Similarly, the CSC population as defined by the cell surface markers CD44+/CD24- was significantly increased in both breast cancer cell lines by leptin." (PMID 28542577, 2017). "Our results also show that circulating leptin levels were significantly higher in ER positive breast cancer patients than ER negative patients, This might have been because of estradiol independent activation of leptin among breast cancer tissues." (PMID 29088874, 2017). "The contribution of leptin to breast cancer development is evident from pre-clinical studies where mice deficient in leptin or with dysfunctional leptin receptors did not develop transgene-induced mammary tumors and had reduced growth of transplanted tumors." (PMID 28542577, 2017).
breast cancer (continued). "Our data suggest that leptin promotes EMT in breast cancer cells via the upregulation of PKM2 expression as well as activation of PI3K/AKT signaling pathway, and PKM2 might be one of the key points and potential targets for breast cancer therapy." (PMID 27769315, 2016). "Although circulating levels of insulin, IGF-1, GH and LEP in relation to breast cancer have been well studied, less is known about how germline variation in the insulin, IGF, GH, and LEP signaling pathways may affect risk of breast cancer." (PMID 27942580, 2016). "A growing body of evidence indicates a crucial role of leptin in the pathogenesis of breast cancer." (PMID 26899873, 2016). "Notch, IL-1 and leptin are known pro-angiogenic inducing factors in breast cancer." (PMID 27472371, 2016). "Since insulin and leptin increase the expression of Sam68, this protein may be a point of convergence for different signals involved in breast cancer growth and progression." (PMID 27415018, 2016). "Leptin is mitogenic for hematopoietic cells, normal and transformed epithelial cells and vascular endothelial cells and has been shown experimentally to stimulate proliferation of breast cancer, hepatoma and prostate cancer cells." (PMID 27050378, 2016). "The role of leptin in mediating the crosstalk between the tumor microenvironment and breast cancer cells remains unclear." (PMID 27588409, 2016). "It is firstly revealed in this study that leptin not only induces breast cancer cells EMT, but also upregulates PKM2 expression; however, the underlying mechanism remains unknown." (PMID 27769315, 2016). "Nevertheless, residual leptin, which may remain on the M2 macrophages even after extensive wash, could diffuse into the chamber of breast cancer cells and directly induce cancer cell migration and invasion." (PMID 27588409, 2016). "Taken together, these data demonstrate that modulation of SOCS3 expression may represent a mechanism through which FXR activation could affect leptin activity on breast cancer." (PMID 26899873, 2016). "In the current study, to minimize the direct stimulatory effects of leptin on breast cancer cells, we washed the leptin-treated M2 macrophages extensively before loading them in the transwell co-culture system to analyze breast cancer cell migration and invasion." (PMID 27588409, 2016). "Moreover, in breast cancer, leptin induces Src/Gbr2/Gab2/STAT3 activation and Rac-1 crosstalk to facilitate VEGF/VEGFR2 activation." (PMID 27472371, 2016). "In a nude mice xenograft model of breast cancer (n = 5 per group), injection of leptin (0.1 μg/g) dramatically increased tumor volume and mass, reduced survival, exacerbated pulmonary metastasis, and elevated IL-8 and Ki67 expression in the tumor tissue (All P < 0.05) compared with PBS injection." (PMID 27588409, 2016). "Furthermore, leptin is angiogenic during tumorigenesis, and insulin is involved in type-2 diabetes-mediated mammary tumor progression in mice." (PMID 27582541, 2016). "Besides, MCF7 cells have been successfully used as a pathophysiological approach for insulin and leptin-related breast cancer in previous works." (PMID 27415018, 2016). "Furthermore, blocking leptin signaling by using a full leptin receptor antagonist significantly reduced mammosphere formation in breast cancer cell lines and patient-derived samples." (PMID 26556856, 2016). "A meta-analysis reported that women with breast cancer have elevated plasma leptin levels." (PMID 27042159, 2016). "The insulin, IGF, GH and LEP pathways are well-characterized in the biological literature, and previous literature suggests important functions or potential functions for each of these genes in breast cancer." (PMID 27942580, 2016). "Plasma leptin data have to be interpreted with caution since leptin and the two main isoforms of its receptor are expressed in 84% of breast cancers, suggesting that cells within tumors can respond to leptin via autocrine as well as paracrine and endocrine pathways." (PMID 27338371, 2016).
breast cancer (continued). "Leptin promoted cell proliferation and homotypic tumor cell adhesion through increased expression of E-cadherin and cyclin D1 in vivo in breast cancer xenograft and in vitro in breast cancer cell lines." (PMID 27185268, 2016). "In summary, our study suggest that leptin may promote breast cancer progression by stimulating IL-8 production in M2 macrophage." (PMID 27588409, 2016). "Importantly, we also showed that leptin is able to increase the mammosphere formation and self-renewal activity in metastatic breast cancer cells isolated from patients." (PMID 26556856, 2016). "More recent studies showed that leptin induced expressions of Notch1, 3, 4 in breast cancer cells, and inhibition of leptin signaling, led to decreased protein expression levels of NICD1, NICD4, Notch3, JAG1 and survivin as well as reduced mRNA levels of Notch receptors, ligands and targets." (PMID 27185268, 2016). "Our results show that activated FXR may be able to counteract the leptin-dependent paracrine effects on breast cancer restraining the tumor-promoting activities exerted by CAFs." (PMID 26899873, 2016). "Thereby, we hypothesized that leptin promoted epithelial-mesenchymal transition of breast cancer cells via the upregulation of pyruvate kinase M2." (PMID 27769315, 2016). "Our previous studies demonstrated that leptin could promote EMT in breast cancer cells, and IL-8 was one of the key molecules which affected leptin-mediated EMT." (PMID 27769315, 2016). "Previous studies showed that leptin activated Notch signaling, which could be involved in the proliferation and migration of breast cancer cells and poor prognosis of breast cancer." (PMID 27185268, 2016). "Thus, we conducted time-course studies to examine the effects of peptide LDFI on phosphorylation of the major leptin signalling molecules, that are known to mediate proliferation and motility in breast cancer cells, using immunoblot analysis." (PMID 25721149, 2015). "This approach could be combined with treatments with CCL2 blocking antibody and the anti-leptin signaling peptide in obese tumor-bearing mice, aiming to inhibit macrophage recruitment/activity in the mammary tumor microenvironment." (PMID 25599228, 2015). "The unmodified peptide LDFI acting as a full leptin antagonist could become an attractive option for breast cancer treatment, especially in obese women." (PMID 25721149, 2015). "In addition to stimulating cell division, leptin can transform breast cancer cells into malignant forms." (PMID 26199932, 2015). "Here, we specifically examined if HNK could inhibit the oncogenic effects of leptin on breast cancer growth and metastatic properties using well-characterized human breast cancer cell lines (MCF-7, MDA-MB-231, MDA-MB-468 and T47D) as models." (PMID 26036628, 2015). "Indeed, leptin signalling in human breast cancer cells enhances aromatase gene expression promoting in situ oestrogen production 22 and directly transactivates oestrogen receptor alpha (ERα) 17,23." (PMID 25721149, 2015). "Leptin gene is expressed in normal breast tissue, breast cancer cell lines, and solid tumors." (PMID 26199932, 2015). "In conclusion, we uncover a novel role of HNK as an effective leptin-antagonist that inhibits leptin-induced growth of breast cancer cells in vitro and in vivo, which involves activation of miR-34a facilitating HNK-mediated inhibition of Wnt1-MTA1-β-catenin axis." (PMID 26036628, 2015). "Leptin—the central regulator of satiety in the body—has been characterized as a pro-inflammatory, pro-angiogenic and proliferation-inducing adipokine essential to breast cancer." (PMID 25599228, 2015). "Leptin generally acts through its receptor (Ob-R), which is encoded by the Ob gene and activates JAK/STAT (Janus kinase/signal transducer) signaling pathway that increases cell migration and invasion of breast cancer cells." (PMID 26431176, 2015).
breast cancer (continued). "Leptin is essential for the growth of human mammary gland and recent studies have shown that it may be effective in breast cancer." (PMID 26199932, 2015). "Our finding that HNK modulates Akt, GSK3β, and β-catenin, key components of leptin-signaling network in breast cancer cells, prompted us to further explore whether HNK treatment can also inhibit MTA1, Wnt1, β-catenin and cyclin D1 in the presence of leptin." (PMID 26036628, 2015). "However, as with leptin, evidence linking adiponectin to recurrence or survival is mixed, and adiponectin and its receptors have been detected in breast cancer tissue indicating that autocrine as well as paracrine and endocrine pathways are operative." (PMID 26132992, 2015). "Also, that in addition to CCL2, leptin and lauric acid, there are additional unidentified paracrine factors promoting monocyte chemotaxis to the obese mammary tumor microenvironment." (PMID 25599228, 2015). "Taken together, our in vitro results modeling the role of leptin in the mammary tumor microenvironment of obese females suggest that leptin’s presence where it is produced by adipocytes, the bAT, seems to play a moderate role by itself in macrophage recruitment." (PMID 25599228, 2015). "Genetically obese leptin-deficient Lepob/ob and leptin receptor-deficient Leprdb/db mice do not develop mammary tumours which provide evidence that leptin and its receptor are involved in breast tumourigenesis 11,12." (PMID 25721149, 2015). "Our results also demonstrate that co-culture with the tumor cells and/or macrophages decreases leptin production by adipocytes, suggesting that in the obese mammary tumor microenvironment of our E0771 DIO tumor model, leptin amounts may be lowered." (PMID 25599228, 2015). "Previously, our group demonstrated that ASCs isolated from obese women (obASCs) also express higher levels of leptin relative to ASCs isolated from lean women (lnASCs) and that this obASC-derived leptin may account for enhanced breast cancer cell growth." (PMID 26286584, 2015). "Plasma leptin data have to be interpreted with caution since leptin and the two main isoforms of its receptor have been reported to be expressed in 84% of breast cancers suggesting that cells within tumors can respond to leptin via autocrine as well as paracrine and endocrine pathways." (PMID 26132992, 2015). "We further investigated the in vivo physiological relevance of our in vitro findings by evaluating whether HNK treatment had inhibitory effects on the development of breast carcinoma in leptin-treated nude mouse models." (PMID 26036628, 2015). "Using the same E0771 mammary tumor cells and several human breast cancer cell lines we recently reported that when exposed to leptin, breast cancer cells express higher protein levels of Notch 3, as we also found in the present study in macrophages exposed to low leptin concentrations." (PMID 25599228, 2015). "Importantly, leptin-induced breast cancer cell proliferation was abrogated by SK1-specific small interfering RNA (siRNA)." (PMID 25482303, 2014). "Nevertheless, present findings might indicate that TNBC could greatly depend on leptin’s actions, which could underline the role of NILCO in this breast cancer type." (PMID 24716804, 2014). "In breast cancer, for example, LEPR 223Arg was associated with increased serum Leptin levels." (PMID 26034683, 2014). "In summary, we demonstrated that curcumin could inhibit expression and secretion of leptin in T47D breast cancer cells." (PMID 25866478, 2014). "Similar to obese women, rodents with high leptin levels are more likely to develop mammary tumors." (PMID 25360510, 2014).